DNAJA1 (DnaJ heat shock protein family (Hsp40) member A1)
Diseases named in the same sentence as DNAJA1 in open-access papers (continued):
Sharing a sentence is not in itself a finding about the gene and the disease.
cancer (24 papers, 2016 to 2025). A tumor composed of atypical neoplastic, often pleomorphic cells that invade other tissues. "This is further supported by the results of the pull-down assay where three (ANT3, glutamate dehydrogenase, and creatine kinase) of the potential protein binding partners of DNAJA1 have been implicated in cancer progression." (PMID 36291603, 2022). "To confirm this role, we screened the NIH Approved Oncology collection for chemical-genetic interactions with loss of DNAJA1 in cancer." (PMID 32796891, 2020). "DNAJA1/HDJ2 is also implicated in progression of multiple types of cancer." (PMID 34948322, 2021). "The increase in DNAJA1 expression in other cancers piqued further interest in its potential role as a therapeutic target." (PMID 36291603, 2022). "Recent efforts have focused on targeting chaperone function in cancer by either manipulating the "chaperone code" or inhibiting helper cochaperones, such as DNAJA1." (PMID 33837724, 2021). "As a first step, we queried the cBioPortal cancer genomic database (cbioportal.org) to determine the incidence of DNAJA1 alterations in cancer." (PMID 32796891, 2020). "Here, we performed an unbiased screen of the NIH Approved Oncology Drug set containing 131 anti-cancer drugs in combination with HAP1 cancer cell lines depleted of J-protein DNAJA1." (PMID 32796891, 2020). "While the roles of Hsp90 and Hsp70 in cancer have been thoroughly studied, much less is known of the role that regulatory co-chaperone proteins such as DNAJA1 play in tumorigenesis." (PMID 32796891, 2020). "Taken together, these results confirm that DNAJA1 is a hub for anticancer drug resistance and that DNAJA1 inhibition is a potent strategy to sensitize cancer cells to current and future therapeutics." (PMID 32796891, 2020). "Analysis of data from 176 non-redundant studies representing 44,347 patient samples revealed that DNAJA1 was altered at a frequency of greater than 1% in 35 cancer types." (PMID 32796891, 2020). "The human homologue of Ydj1 is HDJ2 (also known as DNAJA1), a protein implicated in regulating HIV replication as well as cancer cell growth." (PMID 30452489, 2018). "Importantly, inhibition of DNAJA1 with the small molecule 116–9e promotes R2B degradation and sensitizes cancer cells to RNR inhibitors such as hydroxyurea and triapine." (PMID 38309209, 2024). "After chemogenomic screening the NIH Approved Oncology collection and testing DNAJA1 inhibitors in CRPR-related models, the researchers delineated DNAJA1 as a hub for anticancer drug resistance and suggested that DNAJA1 inhibition is a potent strategy to sensitize cancer cells to chemotherapy." (PMID 34943954, 2021). "DNAJA1/HDJ2 also binds to an enzyme involved in extracellular matrix cross-linking and remodeling, transglutaminase 2 (TG2) that is associated with cell survival and cancer progression." (PMID 34948322, 2021). "We found DNAJA1 to be upregulated in a variety of cancers, suggesting a role in malignancy." (PMID 32796891, 2020). "While beyond the scope of this study, it is possible that the high levels of DNAJA1 expression observed may be a result of increased transcription brought on hyperactive signaling pathways common in cancer cells." (PMID 32796891, 2020).
cancer (continued). "Interestingly, DNAJA1 mRNA was expressed at significantly higher levels in these samples, with a median expression in cancer over 3,000 × relative to WT reference samples." (PMID 32796891, 2020). "To determine whether the DNAJA1 expression is also overexpressed in cancer, we analyzed DNAJA1 mRNA expression in samples from the TGCA PAN-CAN Atlas." (PMID 32796891, 2020). "Although the majority of alterations in DNAJA1 occur at a relatively low frequency (< 5% of cancers) DNAJA1 is significantly amplified in prostate neuroendocrine cancer (PNC) and castration-resistant prostate cancer at a frequency of 17.31% and 17.14% respectively." (PMID 32796891, 2020). "We validated three drugs (cabozantinib, clofarabine and vinblastine) in combination with a unique DNAJA1 inhibitor (116-9e) for synergy in the LNCaP cancer cell lines and confirmed omacetaxine mepesuccinate, idarubicin and sorafenib for antagonism (i.e. with reduced potency after DNAJA1 inhibition)." (PMID 32796891, 2020). "We propose that targeting DNAJA1 in cancer may offer an attractive alternative to the toxicity induced by full Hsp90/Hsp70 inhibition." (PMID 32796891, 2020). "Interestingly, DNAJA1 despite being substantially overexpressed in a range of cancers, there was minimal correlation between DNAJA1 copy number and level of expression." (PMID 32796891, 2020). "Given the cancer-promoting role of DNAJA1/HDJ2, DNAJA1/HDJ2 can be a potential target for cancer therapy." (PMID 34948322, 2021). "Our results indicate that DNAJA1 and DNAJA2 are functional homologues of yeast YDJ1 and play a role in the protection of cells from cytotoxic stresses such as those exerted by cancer chemotherapeutic agents." (PMID 32149145, 2020). "Interestingly, there was minimal correlation between amount of amplification and DNAJA1 expression (r = 0.45) suggesting that while DNAJA1 may be an important marker in cancer it is not caused by gene amplification." (PMID 32796891, 2020). "Although the role of Hsp70 in cancer development is well documented, data concerning the function of its most abundant cellular co-chaperones, Hdj1 (DNAJB1) and Hdj2 (DNAJA1), in the process remain elusive." (PMID 26959111, 2016). "A chemogenomic screen comparing the small molecule resistance of wild-type HAP1 cells to those lacking DNAJA1 revealed a pleiotropic role for DNAJA1 in cancer." (PMID 38309209, 2024). "We have extended our investigation by evaluating the role of all human DNAJAs (DNAJA1, DNAJA2, DNAJA3, and DNAJA4) in the response of cells to cancer therapeutic agents, such as doxorubicin, cisplatin, and etoposide, and to define cytotoxic stresses such as ROS and heat shock." (PMID 32149145, 2020). "Thus, Dnaja1 plays a nonredundant role in the stabilization of AID and balancing immunity and cancer development indirectly." (PMID 29255456, 2017). "While DNAJA1 is not observed in complex with APE2, it is possible that drugs such as 116-9e and C-86 may have a broad enough specificity to be target regulatory co-chaperones of APE2 in cancer." (PMID 35883419, 2022).
tumor (17 papers, 2010 to 2025). "The large change in drug efficacy linked to DNAJA1 suggests a personalized medicine approach where tumor DNAJA1 status may be used to optimize therapeutic strategy." (PMID 32796891, 2020). "DNAJA1 also stabilizes cell division cycle 45 to promote tumor progression, while it binds to transglutaminase 2 associated with cell survival." (PMID 36316326, 2022). "Following improvement of the efficacy and specificity of PLTFBH analogs to DNAJA1 and evaluation of their pharmacological properties, it is crucial to test their in vivo effects on tumor progression, as well as toxicity and safety, using pre-clinical studies." (PMID 36077724, 2022). "In vivo functional assays indicated that DNAJA1 promoted tumor growth and pulmonary metastasis in mice." (PMID 35586205, 2022). "P03 subcutaneous implanted in C57BL/6J mice treated with GY1-22 at 1 mg/kg, i.p. injection (n = 6 mice), showed a significant inhibition of in vivo tumor growth, which was comparable with P03 DNAJA1 knockout line." (PMID 33208462, 2021). "DNAJA1 knockout alone exhibited a significant inhibition of tumor growth 2 weeks after transplantation." (PMID 33208462, 2021). "This leads to changes in the actin cytoskeleton indicating that DNAJA1 is important for prevention of the amoeboid-like transition of tumor cells." (PMID 32796891, 2020). "DnaJA1 function in tumor development is still controversial." (PMID 35570564, 2022). "In summary, DNAJA1 profoundly boosts tumor growth and metastasis in vivo." (PMID 35586205, 2022). "DnaJA1 increased the proliferation, invasion, and metastasis of tumor cells." (PMID 35570564, 2022). "Studies have shown that DNAJA1 also participated in the tumor progression." (PMID 35586205, 2022). "We then evaluated the effect of DNAJA1 on tumor growth, metastasis, and angiogenesis in vivo." (PMID 35586205, 2022). "Moreover, there were less number of vascular in primary tumor of liver in DNAJA1 shRNA group than that in the control group (Figure 4dP < 0.05)." (PMID 35586205, 2022). "The existing literature is contradictory as to whether DNAJA1 may possess tumor suppressor or driver properties." (PMID 32796891, 2020). "This study demonstrates the validity of developing Hsp70 co-chaperone inhibitors to sensitize cells to current anticancer therapies and suggests that determining DNAJA1 status of a tumor may be beneficial in selecting the most appropriate course of treatment." (PMID 32796891, 2020). "For instance, A-type (DNAJA1,3) and B-type (DNAJB4,6) protein expression has been shown to negatively affect tumor cell migration." (PMID 41369326, 2025). "Compared with normal tissues, six proteins (GALNT6A, FOXO1, ACSM3, DNAJA1, PRDX5, and SERPINB9) were notably overexpressed in tumour tissues." (PMID 39030559, 2024). "The up-regulated genes following treatment included heat shock family proteins such as HSP90AA1, HSPA8, DNAJB12, HSPA1L, DNAJA1, HSPA4L, consistently with other array studies in different tumor cell types." (PMID 20920318, 2010).
infection (3 papers, 2011 to 2024). The state of being infected such as from the introduction of a foreign agent such as serum, vaccine, antigenic substance or organism. "Interestingly, in cluster 3 of DEGs between normal + infection group and undernutrition 75% + infection group, hub genes Dnaja1 (0.49-fold change), Hspa1a (0.12-fold change), Hspa1b (0.20-fold change) and Hsph1 (0.35-fold change) were also downregulated in undernutrition 75% + infection group." (PMID 38185681, 2024). "According to our analysis above, the difference between YN13 and YN144 in replication ability might be due to the difference between the two PEDV-infection groups in alterations of eIF4G1, hnRNPA1, HSP90B1, HSP90AB1, HSPA8, DNAJA1, and DNAJC10 in jejunums of pigs." (PMID 27916855, 2016).
infectious disease (1 paper, 2020). A disorder directly resulting from the presence and activity of a microbial, viral, or parasitic agent in humans. "The unique network of upregulated genes in VaD was centered on DnaJ heat shock protein family (DNAJA1) and pre-mRNA processing factor 40 homolog A (PRPF40A) and were enriched predominantly in infectious diseases and inflammatory pathways." (PMID 32192109, 2020).
DNAJA1 also shares sentences with these, for which no sentence is quoted: neurodegenerative disease (3 papers); Infertility (2); tauopathies (2); asthenozoospermia (1); atherosclerosis (1); Azoospermia (1); brain tumor (1); Cirrhosis (1); COVID-19 (1); cystic fibrosis (1); dyslipidemia (1); gastric adenocarcinoma (1); head and neck squamous cell carcinoma (1); Hypertension (1); Hypoglycemia (1); lung carcinoma (1); male infertile (1); myocardial infarction (1); oculopharyngeal muscular dystrophy (1); ovarian tumors (1); pancreatic ductal adenocarcinoma (1); Parkinsonism (1); reproductive diseases (1); sarcoma (1).